CD44 (CD44 molecule (IN blood group))
Diseases named in the same sentence as CD44 in open-access papers (continued):
Sharing a sentence is not in itself a finding about the gene and the disease.
cancer (continued). "Nevertheless, our sorting data indicated that, compared to A549, the H1299 cell line was enriched in constitutive subpopulations of cells carrying CD44+ and CD133+ markers of cancer stem cells (CSCs)." (PMID 35563313, 2022). "The expression of cancer stem cell markers CD24 and CD44, cytokeratins, and vimentin was investigated by immunofluorescence." (PMID 35563359, 2022). "It has been reported that CD44, MKI67 and TYMS are overexpressed in many cancer types, including DTC, and regulate glucose metabolism by targeting different genes." (PMID 35528004, 2022). "As shown, CD44, YAP and CPT1A RNA levels were all significantly increased in cancer tissues and were pairwise positively correlated." (PMID 35359362, 2022). "The NPs targeted cancer cells with recognition of cluster of differentiation 44 (CD44) by HA, while co-injected anti-OX40 antibody (αOX40) reversed the immunosuppressive effect, allowing NPs to enter cancer cells favorably and release drug for chemotherapy." (PMID 36627891, 2022). "The purpose of this article is to provide a better understanding of specific markers such as CD44+/CD24-low and ALDH enzymes in cancer stem cells in the prognosis of TNBC." (PMID 36120232, 2022). "Expression of cancer stem cell markers (CD133, CD44, ganglioside GD2) was significantly increased in A375 spheres, as detected by flow cytometry." (PMID 35847038, 2022). "Co-expression of the autophagy marker LC3 with stem cell markers CD133, CD44 and ALDH1 in pancreatic cancer tissue samples is another example in support of the positive correlation between autophagy and cancer cell stemness." (PMID 36505808, 2022). "The PDAC cells were divided into three states according to CA2 and CD44 expression levels: “State 1” as CA2(-)CD44(+) CICs, “State 2” as CA2(+)CD44(-) differentiated ductal-like cancer cells, and “State 3” as CD44/CA2-negative cells." (PMID 35673567, 2022). "In this study, we performed CD44 and MAL costaining in the collected GC samples to identify the level of the MAL protein in cancer cells expressing stemness markers as a method to assess the relationship between MAL protein levels and cancer stemness." (PMID 35093120, 2022). "Following those phenotypes, it has been described that the expression of stem cell transcription factors, such as CD44, SOX2, CD133 ABCG2, and Nanog, play a pivotal role in determining the aggressiveness of cancer." (PMID 35884836, 2022). "CD44, a transmembrane receptor for hyaluronic acid (HA) and other ECM molecules, is a well-known glycoprotein, often overexpressed in several cancers and reported as a major carrier of truncated O-glycans in gastric cancer cells." (PMID 35205658, 2022). "Cancer stem cells (CSCs) play an important role in the maintenance, recurrence, metastasis, and drug resistance of CRC, and CD44, CD133, CD166, and CXCR4 are putative surface markers of colorectal CSCs." (PMID 35313878, 2022). "Cancer cells that undergo an EMT acquire cancer stem-cell-like properties and show an increase in CD44 expression." (PMID 35024436, 2022). "Cancer cells with an EMT phenotype acquire stem cell-like properties and detected high CD44 expression." (PMID 35931675, 2022). "In recent years, different cancer stem cell populations have been reported in colon cancer, as defined by the markers LGR5+, CD44+, and ALDH positive activity, among others." (PMID 35954194, 2022). "Signaling born from the intracellular portion of CD44 activates Ras, MAPK, PI3K, and RUNX2-RANKL pathways.CD44 is a marker of cancer stem cells (CSCs) and regulates stemness." (PMID 35626089, 2022). "On these bases, we developed CS/HY NPs, able to interact with CD44-transmebrane receptors, for selective delivery of VBL to cancer cells." (PMID 35631528, 2022). "CD133+CD44+ cells have CSC characteristics and CD133−CD44− cells have regular cancer cell characteristics." (PMID 35485210, 2022).
cancer (continued). "CAE induced a dose-dependent increase in cell migration and invasion and also in the expression of cancer stem cells markers (CD133, CD44, CD90)." (PMID 35713728, 2022). "Furthermore, apoptosis in cancer cells may be triggered by anti-CD44 antibodies." (PMID 36613567, 2022). "Markers of HCC stem cells, including CD44, EPCAM, and THYI (CD90), were expressed at the beginning of the cancer cell differentiation trajectory." (PMID 35967424, 2022). "Many targets, including PDGFR, CD44, CSF1R and NTRK2, have small-molecule inhibitors approved for clinical use or are currently under clinical trials for cancer treatment, including glioblastoma." (PMID 36216799, 2022). "We observed top-ranking ligand-receptor pairs of macrophage migration inhibitory factor (MIF) in cancer cells and (CD74+CD44) in macrophages." (PMID 36248860, 2022). "CD24 in combination with CD44 and/or CD133 (PROM1) has been highlighted as cancer stem cell markers (in combination with NANOG, OCT3/4, and SOX2), and a cell‐type‐dependent correlation of CD24 to the chemokine receptor CD184 (CXCR4) has been shown." (PMID 34293822, 2022). "Our results showed that SJZ treatment inhibited the spheroid and colony-forming capacities of SGC7901 cells, accompanied by downregulation of cancer stem cell markers such as SOX2, NANOG, and CD44." (PMID 35873650, 2022). "For example, OC-derived exosomes carrying CD44 reprogramed mesothelial cells to a more EMT phenotype, which facilitated cancer adhesion and invasion." (PMID 36268019, 2022). "The mechanism of action of C9-PEX, through which it antagonizes the interaction of MMP9 with CD44, leads to the suppression of ECM degradation and subsequently cancer cell migration and invasion." (PMID 35406619, 2022). "Immunohistochemistry (IHC) and proteomic analysis showed pronounced decrease in cancer stem cell biomarkers (CCD117, CD34, Oct-4, CD44, and CD-24) and metastatic biomarkers such as Notch-1." (PMID 35335986, 2022). "We then identified the involvement of CD44 in the effect of CBS/H2S axis on CRC cells, which is a well-known transmembrane marker for its pro-cancer and stemness-maintenance function." (PMID 35172821, 2022). "Among the EOC tissues examined, CXCR4 expression correlated strongly with expression of proteins related to the epithelial-mesenchymal transition (EMT) and cancer stem cell (CSC), including vimentin, N-cadherin, E-cadherin, CD44, CD133, and NANOG." (PMID 35681259, 2022). "To further verify ERK pathway involvement in the regulation of cancer stemness, we analysed the stem surface markers of CD133, CD44, and CD24." (PMID 36386200, 2022). "Cancer stem cells (CSCs), characterized by CD24-, CD44-, and EpCAM-positivity in pancreatic cells, play important roles in metastasis and chemoresistance." (PMID 35846884, 2022). "The human CD44/MYC-high cluster expressed CENPK and CENPN, which regulate the cell cycle and cell division in cancer." (PMID 35611554, 2022). "As demonstrated in the top DEGs, specifically cancer stem lineage clusters expressed high levels of stemness feature genes (MKI67, CD44, CD24, and PROM1) and key DEeRNAs (PHLDA1 and RASD1)." (PMID 36092920, 2022). "Previous studies had shown that cancer stem cells maintain their stem cell-like biological characteristics through a high expression of specific stemness markers (such as SOX2, CD44, CD133, and MYC)." (PMID 35859724, 2022). "CD44 is considered to be one of the most common CSC surface markers, responsible for the regulation of cancer cell stemness." (PMID 36297407, 2022). "In breast cancer, there are two types of cancer stem cells: CD44+/CD24 mesenchymal-like cancer stem cells and aldehyde dehydrogenase 1 family, member A1 (ALDH1) positive epithelial-like cancer stem cells." (PMID 35328602, 2022).
cancer (continued). "CD44 is a non-kinase transmembrane glycoprotein, also referred to as extracellular matrix receptor III (ECMR-III), P-glycoprotein 1 (Pgp-1), and HUTCH-1, that is widely expressed on the surface of vertebrate cells, especially cancer stem cells." (PMID 36293491, 2022). "Lastly, circ_001680 has been found to promote several cancer stem cell characteristics, such as sphere formation ability, elevated expression of stem cell characteristic markers (SOX2, CD44, and CD133), and irinotecan resistance." (PMID 36429127, 2022). "Expression analysis detected HMGA1-high cancer cells (HMGA1 expression level>2), CD44-high cancer cells (CD44 expression level>2) and double-positive cancer cells in the integrated TNBC cohorts." (PMID 35611554, 2022). "Up to now, Wnt/β-catenin signaling has been considered as the key factor in regulating cancer stem cells, and masses of cancer stemness-related genes (OCT4, ALDH1A1, LGR5, CD44, c-Myc, SOX2, and so on) are regulated by Wnt/β-catenin signaling." (PMID 36319622, 2022). "Upon fusion with macrophages, both MCF-7 and MDA-MB-231 cells had a higher percentage of CD44+/CD24−cells and enhanced tumorigenicity in vivo, suggesting that cell fusion can also be a source of cancer stem cells (CSCs)." (PMID 35242760, 2022). "Several molecules such as CD24, CD44, and CD133 have been recognized as CSC markers for certain cancer types; however, the roles of these markers are ambiguous." (PMID 35395804, 2022). "CD44 and TGF-β have been considered essential markers for cell proliferation and cancer progression for many years." (PMID 35269524, 2022). "The 12 FRGs are divided into 4 categories according to their functions: lipid metabolism (GPX4, LPCAT3, ACSL5, ACSL6), antioxidant (CD44, SESN2, AIFM2), iron metabolism (CISD1, HSPB1), and cancer metabolism (SOCS1, FH, G3BP1)." (PMID 35559049, 2022). "Current research has also found that SIPA1 protein can prove breast cancer cell stemness by targeting the CD44 gene, and enhance aerobic glycolysis of cancer cells by targeting the EPAS1 gene to promote cancer cell metastasis." (PMID 36230738, 2022). "Based on function, the 12 FRGs can be grouped into four classes: Lipid metabolism (GPX4, LPCAT3, ACSL5, and ACSL6), antioxidant metabolism (CD44, SESN2, and AIFM2), iron metabolism (CISD1 and HSPB1), and cancer metabolism (SOCS1, FH, and G3BP1)." (PMID 34784264, 2022). "We found that human cancer clusters showed specific gene expression patterns for high-mobility group AT-hook 1 (HMGA1) and CD44." (PMID 35611554, 2022). "In our investigation, we observed a higher expression of CD44 in cell lines with high PKM2 and P-PKM2 Tyr105 levels, indicating a connection between PKM2 and cancer stemness in HNSCC as well." (PMID 35054968, 2022). "Among the selected cancer stemness genes, we found that TERT, MYC, CD44, BMI1, ABCB1 and ABCG2 were highly expressed in OCM1 cells compared to their expression in C918 cells, whereas the expression of ZEB1 was opposite to that of the stemness genes." (PMID 35404029, 2022). "Cancer cell targeting via HA receptors was investigated using HA-modified PCL-PEG MPMs, where the external HA layer was created to link CD44 in lung cancer." (PMID 36233094, 2022). "In particular, cluster 11 had high expression levels of cancer stem cell (CSC) marker genes, including NOTCH1, KLF4, CD44, EPAS1, and MYC." (PMID 36618022, 2022). "In HCC, CD44 and CD133 are common cancer stem cell (CSC) markers, CD133+ cells have stronger proliferation ability and tumorigenicity than CD133 cells, while CD44 provides a unique cellular signature for CD133+ or CD90+ CSCs in HCC." (PMID 35756606, 2022). "CD44, one of the most common CSC surface marker, is widely accepted as a key regulator of cancer stemness." (PMID 35229451, 2022). "Since CD44 and BMI1 are well known cancer stem cell markers, we also investigated the effect of miR-3928 on GBM stem cells (GSCs)." (PMID 35409289, 2022).
cancer (continued). "Eleven of those proteins were detected in all patients, including the common EV markers CD9, CD63 and CD81, cancer-related markers CD24, CD29, CD44 and CD146, platelet markers CD41b, CD42a and CD62p as well as HLA-DR/DP/DQ." (PMID 35012489, 2022). "Others and we found that CD44 acts as a regulator of EMT and epithelial plasticity in breast, pancreatic and other cancers." (PMID 35931675, 2022). "The EVs have several cancer-related markers including CD24, CD29, CD44 and CD146, proteins of potential interest as biomarkers as well as to increase the understanding of the mechanisms of cancer biology." (PMID 35012489, 2022). "Here, we investigated the transcriptional silencing of the CD24, CD44, CD133, and CD147 genes, which are well-known cancer stem cell surface markers in various cancer types, including OSCC." (PMID 36498950, 2022). "In particular, for the therapy of AML, which requires greater cancer cell specificity, in pioneer studies, CAR T cells targeting antigens CD33, CD44, and CD123 have been developed." (PMID 35990606, 2022). "Generally, the most significant cancer stem cell markers related to the Notch pathway are CD133, Musashi-1, CD44, EpCAM, CD166, and Bmi1." (PMID 36429127, 2022). "The current study further investigated the potential involvement of cancer stemness in these MRE11-promoting effects, leading to the findings of CD44 as a downstream effector of MRE11." (PMID 35629265, 2022). "Oligo-HA has demonstrated other preventive properties in cancer, for instance, by interfering with the endogenous interaction of HMW-HA with CD44." (PMID 36613567, 2022). "As HA is a targeting agent to cancer cells overexpressing CD44, HA–DPPE conjugates facilitate the recognition of modified liposomes by MiaPaCa2 cells expressing CD44, and the uptake increases with increasing molecular weight of HA from 4800 to 12,000 Da." (PMID 35456613, 2022). "CD44 plays a role in remodeling and degradation of a key component of the extracellular matrix (ECM) hyaluronan leading to cell migration, cancer expansion, and metastasis." (PMID 36474162, 2022). "In addition, CDC42, together with cell adhesion molecule CD44, were found to be crucial for the motility of cancer cells as they are highly concentrated in the flectopodia, the actin-based cytoplasmic extensions on the cancer cell membrane that impact the contractile activity of pericytes." (PMID 36119528, 2022). "CD44, as a critical biomarker of stem cells, has been reported to be involved in epithelial mesenchymal transition (EMT) during cancer progression." (PMID 35034634, 2022). "These CD44 targeting strategies using HA-based therapeutic NGs can significantly enhance drug (etoposide, salinomycin, curcumin) bioavailability, and treat MDR cancer cells and multicellular spheroids." (PMID 36559325, 2022). "Among the identified AS targets, specific CD44 and NUMB isoforms were shown to play specific and unexpected roles in stemness and cancer." (PMID 36346211, 2022). "Thus, activating in-cell killing by anti-CD44 antibody that works together with either endogenous or infused exogenous NK cells may preferentially kill CSC for some types of cancers, reducing the frequency of relapse which warrants further investigation in the future." (PMID 35436988, 2022). "In order to investigate the effect of butylidenephthalide on the expression of cancer stemness markers, we tested the proportion of cells that express ALDH1 or CD44 after treatment with various concentrations of butylidenephthalide." (PMID 35682836, 2022). "Using SEC isolation, a large number of EVs were isolated and surface protein profiling revealed that the EVs contain several cancer-related markers, including CD29, CD44 and CD146." (PMID 35012489, 2022). "Here, we have focused on CD44 and NUMB as two ESRP1-specific AS target genes with well-established functional roles in EMT and in cancer invasion and metastasis." (PMID 36346211, 2022).
cancer (continued). "CD44, integrins, and MCT1 have also been reported to play key roles in cell adhesion, survival, and metabolism in proliferating cancer cells, and those expressions correlate with a poor prognosis in cancer." (PMID 36385956, 2022). "CD44 increases the invasibility of skin (SF) and endometrial stromal fibroblasts (ESF) by cancer and trophoblast cells." (PMID 36148042, 2022). "TGFβ2 was significantly negatively correlated with mRNAsi and significantly positively correlated with cancer stem cell markers DCLK1, Lgr5, CD133 and CD44." (PMID 35620459, 2022). "To investigate the relationship between the niche factor dependency and cancer stem cell populations, we evaluated the correlation between niche factor dependency and the expression levels of PDAC stem cell markers including CD44, CD24, and CD133." (PMID 35272688, 2022). "We previously found that TNBC PDXs express splicing variants of CD44 (CD44v), whereas MDA-MB-231 cells predominantly express standard CD44 (CD44s), both contributing to CTC cluster formation and cancer metastasis." (PMID 36193887, 2022). "ISL not only inhibited the self-renewal ability but also reduced the expression of cancer stemness markers, including ALDH1 and CD44, in the GRP78-mediated pathway." (PMID 35740372, 2022). "HA holds a crucial role in cancer cell survival, proliferation, and invasion, which can be induced through interactions with both RHAMM and CD44, acting through PI3K, MAPK, NFκB, and RAS, as well as cytoskeletal components required for cancer development." (PMID 35267625, 2022). "Other cancer-related markers that were detected on the surface of the EVs from all patients were CD29, CD44 and CD146." (PMID 35012489, 2022). "To further investigate the relationship between cancer stem cell-like properties and CMTM2, we detected the expression of stem cell markers SOX2, NANOG, and CD44 in SGC7901 cells using qRT-PCR and western blotting." (PMID 35873650, 2022). "CD44 and CD133 are the most widely used markers in cancer stem cell research and are already used as therapeutic targets in cancers." (PMID 36012742, 2022). "Emerging evidence indicates that lipid raft levels are significantly enriched in CSCs compared to cancer cells and that most CSC markers such as CD24, CD44, and CD133 are located in lipid rafts." (PMID 36042526, 2022). "CD44, one of the most common CSC surface marker, is involved in the regulation of cancer cell stemness." (PMID 35229451, 2022). "The reduced expression of αvβ3 integrin and CD44 in DMA alone and DMA with radiation-treated mice suggests a reduced migration of cells and stemness of cancer cells." (PMID 36230831, 2022). "Treatment with 100 mg/kg corylin in the AOM/DSS mice led to significantly decreased cancer stem cell and intestinal epithelial cell proliferation, including LGR5, CD44, Ki67, PCNA, BrdU, and Cyclin D1 levels, compared with the AOM/DSS group." (PMID 35269806, 2022). "It was demonstrated that cancer cells involved in VM show expression of CD133, CD44, ALDH, and Sox2, but also VE-cadherin and CD31." (PMID 36429127, 2022). "For instance, SF epithelial splicing regulatory protein 1 (ESRP1) can regulate expression of CD44 isoforms through AS in MESO and other cancers." (PMID 34041868, 2021). "Cancer stem cells are defined by the expression of a set of different markers such as CD133, CD44, and Nestin." (PMID 33925297, 2021). "In cancer, RFX1 promotes differentiation of CSCs by directly and indirectly targeting major stemness regulators like c-Myc, FGF1, and CD44." (PMID 33964962, 2021). "Our results suggested that SPNs affect both PANC-1 cancer cells and PANC-1 cancer stem-like cells through decreasing CD surface markers CD24, CD44, and CD133." (PMID 34094034, 2021). "We further identified an increase in label retaining and CD44 + CD24− expressing cells, which are markers frequently used to characterize drug resistant cancer stem cells, in these cultures." (PMID 34561423, 2021).